TARDBP (TAR DNA binding protein)
Diseases named in the same sentence as TARDBP in open-access papers (continued):
Sharing a sentence is not in itself a finding about the gene and the disease.
frontotemporal dementia (continued). "Comorbid neurodegenerative disease was present in 25 of the 68 CTE cases (36.8%) including AD, Lewy body disease (LBD), frontotemporal lobar degeneration (FTLD)-TAR DNA-binding protein (TDP), progressive supranuclear palsy (PSP) and Pick’s disease." (PMID 36759368, 2023). "At the pathological level, either the tau or the TAR DNA-binding protein, with a molecular weight of 43 kDA protein (TDP-43), account for almost all cases of frontotemporal lobar degeneration." (PMID 36499048, 2022). "TARDBP mutations have been described in a few cases of ALS, frontotemporal dementia (FTD), or combined presentations thereof, and are thought to facilitate or accelerate such neuropathological alterations." (PMID 35911889, 2022). "In parallel to PTMs, since 2008, many articles have reported disease-associated mutations in the TARDBP gene, supporting the idea of direct involvement of TDP-43 in neurodegenerative disorders, like ALS and frontotemporal lobar degeneration." (PMID 35835219, 2022). "Accordingly, carriers of autosomal dominant mutations in the genes associated with TAR DNA-binding protein 43 aggregation, such as Chromosome 9 open reading frame 72 (C9orf72) or progranulin (GRN), are at risk of later developing frontotemporal dementia." (PMID 36632182, 2022). "Immunohistochemistry showed abundant TAR DNA-binding protein 43 kDa (TDP-43) dystrophic neurite pathology in the frontal and temporal cortex and the dentate gyrus of the hippocampus, consistent with frontotemporal lobar degeneration (FTLD)." (PMID 35327632, 2022). "ALS-affected neurons and glia showed an abnormal aggregation of TAR DNA-binding protein 43 (TDP-43), which is one of pathological hallmark of ALS and multiple forms of frontotemporal lobar degeneration (FTLD)." (PMID 36552734, 2022). "In 2006, it was found that mutations in the TAR DNA-binding protein (TARDBP) gene, which encodes the TDP-43 protein, are responsible for familial cases of ALS and frontotemporal lobar degeneration with TDP-43 inclusions (FTLD-TDP)." (PMID 35563214, 2022). "TARDBP encodes TAR DNA-binding protein 43 (TDP-43), which is a key component of the insoluble and ubiquitinated cytoplasmic inclusions in the brain and spinal cord of ALS and frontotemporal dementia (FTD) patients." (PMID 35954242, 2022). "The TMEM106B and GRN signals in frontotemporal lobar degeneration with TAR DNA-binding protein (TDP-43) inclusions (frontotemporal lobar degeneration TDP) probably share causal variants with ADD (coloc PP4 = 99.8% and coloc PP4 = 80.1%, respectively)." (PMID 35379992, 2022). "The pathological hallmark underlying most of ALS cases and half of the cases of frontotemporal lobar degeneration (FTLD) is the deposition of nuclear and cytoplasmic inclusions of TAR DNA-binding protein 43 (TDP-43) and phosphorylated-TDP-43 (pTDP-43)." (PMID 32803397, 2021). "Different TAR DNA-binding protein (TDP-43) aggregates exist in the brains of Frontotemporal lobar degeneration (FTLD-TDP) subtypes, showing morphological differences across the subtypes." (PMID 34680054, 2021). "Mutations in TARDBP lead to familial ALS and frontotemporal dementia (FTD), indirectly affecting muscle function." (PMID 34616743, 2021). "The pathological hallmarks of ALS are tau-negative and ubiquitin-positive intraneuronal inclusions, and the 43-kDa TAR DNA-binding protein (pTDP-43) is a major component of the inclusions specific for frontotemporal lobar degeneration and ALS." (PMID 34511130, 2021). "Chromosome 17 carries another gene named progranulin (PGRN), that is also linked with the spectrum of frontotemporal dementia-parkinsonism, but with TAR DNA binding protein 43 (TDP43) inclusions instead of tau." (PMID 33250855, 2020). "There are predominantly two pathologic FTD subtypes (i.e., frontotemporal lobar degeneration, FTLD): FTLD-Tau, which has inclusions of the microtubule-associated protein tau, and FTLD-TDP, which has TAR DNA-binding protein 43 (TDP-43) inclusions." (PMID 31019447, 2019).
frontotemporal dementia (continued). "Heterozygous progranulin (PGRN) loss-of-function mutations lead to autosomal dominant transmission of the neurodegenerative disorder frontotemporal lobar degeneration (FTLD) with TAR DNA binding protein 43 (TDP-43) inclusions." (PMID 31398187, 2019). "Heterozygous mutation of the GRN gene is the major cause of FTD-TDP, which is a subtype of frontotemporal dementia (FTD) characterized by ubiquitinated and fragmented TAR-DNA binding protein-43 (TDP-43)." (PMID 31775776, 2019). "TAR DNA binding protein 43 (TDP-43) inclusions and mutations are associated with the development of ALS and some frontotemporal dementias and ALS." (PMID 31791377, 2019). "Aberrant accumulation of TAR DNA-binding protein 43 (TDP-43) is a pathological hallmark of ALS and frontotemporal lobar degeneration (FTLD)." (PMID 31345270, 2019). "For example, the human TAR DNA binding protein 43 (TDP-43) encoded by the TARDBP gene is an evolutionarily conserved gene that has been implicated in multiple neurodegenerative disorders including ALS, frontotemporal dementia, and Alzheimer disease." (PMID 30126171, 2018). "The two most prevalent pathologies within the clinical spectrum of FTD are frontotemporal lobar degeneration (FTLD) with TAR DNA- binding protein 43 inclusions (FTLD-TDP), and FTLD with tau positive inclusions (FTLD-Tau)." (PMID 28827549, 2017). "In 2006, the RNA binding protein TAR DNA-binding protein 43 (TDP-43) encoded by the TARDBP gene was identified as a major component of ubiquitinated aggregates in ALS and frontotemporal lobar degeneration (FTLD)." (PMID 28082870, 2016). "This study identified a family presenting with an autosomal dominant complex P112H TARDBP double variation located in exon 3 with variable clinical phenotype ranging from a pure frontotemporal dementia to pure ALS." (PMID 25853458, 2015). "Mutations in TARDBP (coding for TDP-43) and FUS are described in ALS patients with a family history but also in patients with fronto-temporal dementia (FTD) with a high risk (around 30%) to develop ALS." (PMID 25653590, 2014). "In a previous report, we documented the presence of caspase-cleaved TAR DNA-binding protein (TDP)-43 and caspase-cleaved tau in Pick's disease that revealed an almost identical staining pattern as observed with the nApoECF antibody in the present study." (PMID 24312462, 2013). "The recent discovery of mutations in TAR DNA-binding protein-43 (TDP-43) and Fused in sarcoma (FUS, also named TLS) in both familial ALS and frontotemporal dementia (FTD) has shifted research into disease mechanisms and potential therapeutics." (PMID 22363618, 2012). "Ubiquitin-immunoreactive neuronal inclusions composed of TAR DNA binding protein of 43 kDa (TDP-43) are a major pathological feature of frontotemporal lobar degeneration (FTLD-TDP)." (PMID 22539017, 2012). "In various sALS and fALS cases, abnormal subcellular distribution and cytoplasmic aggregation of TAR DNA binding protein (TDP-43) is widely reported along with frontotemporal lobar degeneration." (PMID 21941533, 2011). "The assembly of TAR DNA-binding protein 43 (TDP-43) into amyloid filaments within neurons is a hallmark of multiple neurodegenerative diseases, including motor neuron diseases (MND), frontotemporal dementias (FTD) and limbic-predominant age-related TDP-43 encephalopathy (LATE)." (PMID 41659424, 2026). "Although TARDBP mutations are a rare cause of ALS, TDP-43 pathology is almost ubiquitous in patients with ALS and is also detected in a large proportion of patients with frontotemporal dementia." (PMID 40252666, 2025). "The most common histopathological finding was frontotemporal lobar degeneration (FTLD) with TAR DNA binding protein 43 (TDP-43) inclusions (n = 8) with hippocampal sclerosis (n = 5/8), FTLD-tau (n = 4), mixed high likelihood Alzheimer’s disease and Lewy body disease (n = 4)." (PMID 38419734, 2024).
frontotemporal dementia (continued). "Seven patients were classified as having definite PSP, and two patients were classified as having TAR DNA-binding protein 43 (TDP-43)-positive frontotemporal lobar degeneration (FTLD-TDP): one with FTLD/MND-TDP and one with FTLD-TDP related to a TANK-binding kinase 1 (TBK1) mutation." (PMID 39580770, 2024). "Frontotemporal lobar degeneration (FTLD) is another type of dementia, in which neurons in the frontal and temporal lobes of the brain are destroyed by the accumulation of TAR DNA binding protein-43 (TDP-43), resulting in extensive memory and function loss." (PMID 37685965, 2023). "TAR DNA-binding protein 43 (TDP-43) is a nucleic acid–binding protein found in the nucleus that accumulates in the cytoplasm under pathological conditions, leading to proteinopathies, such as frontotemporal dementia and ALS." (PMID 35835219, 2022). "The 43-kDa TAR DNA-binding protein (TDP-43) is a ubiquitous DNA binding protein with multiple functions encoded by the TARDBP gene, and its mutations have been associated with autosomal dominant ALS and frontotemporal dementia (FTD)." (PMID 35053327, 2022). "Approximately 50% of cases with frontotemporal lobar degeneration (FTLD), the neuropathological diagnosis of FTD, are characterized by cytoplasmic inclusions containing TAR DNA binding protein 43 (TDP-43) in neurons and glia, with a concomitant loss of nuclear TDP-43." (PMID 35879741, 2022). "Amyotrophic lateral sclerosis 10 (ALS10; OMIM #612069), also known as frontotemporal lobar degeneration with TDP43 inclusions, TARDBP-related (FTLD-TDP, TARDBP-RELATED), is caused by heterozygous mutations in the TAR DNA binding protein gene (TARDBP), which encodes the TDP-43 protein." (PMID 32660023, 2020). "Furthermore, almost all patients with sporadic ALS and more than half of those with frontotemporal dementia (FTD) had TAR DNA‐binding protein 43 (TDP‐43)‐positive ubiquitinated cytoplasmic inclusions." (PMID 33089973, 2020). "TDP-43, encoded by the TARDBP gene located at 1p36.22 on chromosome 1, is a critical element of the tau-negative, ubiquitin-positive inclusions that are hallmark features of both ALS and Frontotemporal lobar degeneration (FTLD) associated with TDP-43 pathology." (PMID 38739934, 2024). "Hence, we evaluated the role of FAM76B in the common neurodegenerative diseases Alzheimer’s disease (AD), frontotemporal lobar degeneration with tau pathology (FTLD-tau), and frontotemporal lobar degeneration with TAR DNA-binding protein 43 inclusions (FTLD-TDP)." (PMID 37643469, 2023). "According to reports from the literature, patients with TARDBP mutations have a broad clinical spectrum, including ALS, frontotemporal dementia (FTD), and parkinsonism, and variations in age of onset and disease progression." (PMID 38002982, 2023). "TDP-43, encoded by the TARDBP gene, is the major aggregated protein involved in the formation of the characteristic inclusions, especially in its hyperphosphorylated and ubiquitin-bound form, in the brains of patients with ubiquitin-positive frontotemporal lobar degeneration (FTLD-U) and or ALS." (PMID 36611365, 2022). "Moreover, some of the genes identified in ALS patients are also causative for other neurodegenerative disorders, such as C9orf72 and TARDBP for frontotemporal dementia (FTD) and Parkinson’s disease, and SPG7 and SPG11 for hereditary spastic paraplegia, indicating shared pathomechanisms." (PMID 35052424, 2021). "ALS is associated with several genes, for example, C9ORF72, TARDBP, SOD1 and FUS, with some genes also contributing to the presence of frontotemporal dementia (FTD)." (PMID 33094283, 2020). "Although TDP-43 is the main constituent of the ubiquitinated cytoplasmic inclusions in the most common forms of frontotemporal lobar degeneration, TARDBP mutations are not a common cause of familial frontotemporal dementia, especially in the absence of motor neuron disease." (PMID 25853458, 2015).
frontotemporal dementia (continued). "TAR DNA binding protein 43 (TDP-43) pathology is the central disease marker of almost all cases of ALS and approximately half of frontotemporal dementia (FTD)." (PMID 41423699, 2025). "For instance, two RNA-binding proteins, TAR DNA-binding protein 43 kDa (TDP-43) and translocated in liposarcoma (FUS/TLS), are abundant in ALS, frontotemporal dementia (FTD), and some AD cases." (PMID 40629391, 2025). "In 2006, the C-terminal TAR DNA-binding protein (referred as C-TDP-43 hereafter) was identified as the major component in the inclusions of ALS and frontotemporal lobar degeneration (FTLD) patients." (PMID 37101169, 2023). "They demonstrated an elevation in clusterin in frontotemporal dementia (FTD), PSP, and CBD—NDDs with dominant tau or TAR DNA-binding protein (TDP)-43 proteinopathy but minimal α-synuclein pathology—as compared to healthy individuals." (PMID 35326174, 2022). "In frontotemporal dementia (FTD), amyloidopathy could be present with main pathologic protein such as tau or TAR DNA-binding protein 43 (TDP-43)." (PMID 36733444, 2022). "TAR DNA binding protein-43 (TDP-43) has become a target for ALS- and frontotemporal dementia-related research, as it was identified as a major component of ubiquitin-positive inclusions." (PMID 34803658, 2021). "Non-4RT FTLD comprised 46 patients with TAR DNA-binding protein 43 (TDP-43) pathology, 10 patients with three-repeat (3R)-tau pathology (Pick’s disease), and four patients with fused in sarcoma (FUS) protein pathology." (PMID 32914550, 2020). "Aβ and tau proteins in AD; α-syn in PD; TAR DNA-binding protein 43 (TDP43), tau, or fused in sarcoma (FUS) proteins in frontotemporal dementia (FTD); and TDP43 in motor neuron disease exhibit some properties of the misfolded prion protein." (PMID 32204380, 2020). "TAR DNA-binding protein 43 (TDP-43) was recently identified as the major pathological protein in sporadic ALS and in the most common pathological subtype of FTD, frontotemporal lobar degeneration with ubiquitinated inclusions (FLTD-U)." (PMID 32962107, 2020). "TAR DNA-binding protein of 43 kDa (TDP-43) accumulates and forms aggregates in the brains of patients with ALS and frontotemporal lobar degeneration (FTLD)." (PMID 30810811, 2019). "TAR DNA binding protein 43 (TDP-43) is another protein detected in pathological inclusions of ALS and cases of frontotemporal lobar degeneration with ubiquitin inclusions." (PMID 25404049, 2015). "TDP-43 (TAR-DNA-binding protein-43) is typically found in cytoplasmic inclusions of patients with motor neuron disease and frontotemporal lobar degeneration." (PMID 23514108, 2013). "Other molecular defects found in IBMPFD patients include mitochondrial dysfunction, the accumulation of ubiquitylated species, and TAR DNA binding protein-43 (TDP-43), a major disease protein in frontotemporal dementia and ALS." (PMID 24167726, 2013). "In 2006, TAR DNA binding protein 43 (TDP-43) was identified as the major protein constituent of ubiquitinated neuronal inclusions in non-SOD1 ALS cases as well as in cases of frontotemporal dementia (FTD) with ubiquitin inclusions." (PMID 22879928, 2012). "Heterozygous mutations in GRN gene lead to insufficient levels of the progranulin (PGRN) protein, resulting in frontotemporal dementia (FTD) with TAR DNA-binding protein 43 (TDP-43) inclusions, classified pathologically as frontotemporal lobar degeneration (FTLD-TDP)." (PMID 40234992, 2025). "Given the patient’s family history of frontotemporal dementia (FTD) in a maternal uncle, the genetic analysis was extended to include the most common genes associated with FTD (TARDBP, GRN, TBK1, CHMP2B, SQSTM1, UBQLN2, VCP and MAPT) but no additional variants of clinical significance were detected." (PMID 40659544, 2025).
frontotemporal dementia (continued). "Frontotemporal lobar degeneration (FTLD) is a neurodegenerative disorder characterised by intracellular accumulation of ALS-related proteins fused in sarcoma (FUS) and TAR DNA-binding protein 43 (TDP43), as well as tau." (PMID 37898823, 2024). "Alzheimer’s disease (AD) and frontotemporal lobar degeneration (FTLD) are characterized by tau and/or TAR DNA-binding protein 43 (TDP-43) inclusions while α-synuclein (α-syn) accumulates in the brain of Parkinson’s disease (PD) and dementia with Lewy bodies (DLB) patients." (PMID 38365772, 2024). "A better understanding of TARDBP and TBK1 could also lead to a better understanding of how they may be responsible for two pathologies, ALS and fronto-temporal dementia (FTD)." (PMID 39201350, 2024). "Frontotemporal lobar degeneration with TDP‐43 inclusions (FTLD‐TDP) is a fatal neurodegenerative disease distinguished by the accumulation of inclusions of hyperphosphorylated and ubiquitinated TAR DNA‐binding protein of 43 kD (TDP‐43), in glia and neurons." (PMID 31808235, 2020). "It should also be pointed out that activation of microglial NLRP3 inflammasome with TAR DNA-binding protein 43 (TDP43)—the major pathological protein in sporadic ALS and the closely related frontotemporal dementia—was shown to be toxic to motoneurons in a microglia-motoneuron co-culture." (PMID 32635451, 2020). "Tar DNA binding protein 43 (TDP-43) was identified as the major constituent of the ubiquitinated protein inclusions present in brain and spinal cord of most cases of ALS and frontotemporal lobar degeneration with ubiquitinated inclusions (FTLD-U), a type of FTD7,8." (PMID 29079747, 2017). "TAR-DNA-binding protein-43 (TDP-43) was identified as the major component of the proteinaceous inclusions present in ~97% ALS and ~45% frontotemporal dementia (FTD) patients, and has also been observed in an increasing spectrum of other neurodegenerative disorders, including Alzheimer disease." (PMID 26735904, 2016). "The nature of the inclusions remained largely unknown until a remarkable discovery identified the TAR DNA binding protein (TDP-43) as a major component in UBIs of ALS and also of Frontotemporal Lobar Degeneration (FTLD-TDP)." (PMID 24740308, 2014). "Neuropathological classification of Frontotemporal Dementia (FTD) is based on the major constituents of the cellular inclusions present, such as tau, TAR-DNA-binding protein-43 (TDP-43) or fused-in-sarcoma (FUS) protein, designated FTLD-tau, FTLD-TDP or FTLD-FUS respectively." (PMID 25188321, 2014). "TAR-DNA binding protein-43 (TDP-43) has recently been identified as the major protein in the ubiquitinated inclusions that characterize frontotemporal lobar degeneration with ubiquitin-positive, tau-negative inclusions (FTLD-U) and motor neurone disease (MND)." (PMID 18657254, 2008). "TAR-DNA binding protein-43 (TDP-43) is the major ubiquitinated protein in the aggregates in frontotemporal dementia with ubiquitin-positive, tau-negative inclusions and motor neurone disease." (PMID 18657254, 2008). "In addition, as described in detail previously TAR DNA-binding protein 43 (TDP-43)-immunoreactive deposition can be detected in neurodegenerative tauopathy, including Alzheimer disease, Pick disease, corticobasal degeneration, progressive supranuclear palsy, and argyrophilic grain disease." (PMID 30922392, 2019). "ALS and frontotemporal dementia (FTD) are clinically distinct disorders that have recently been brought together with the identification of C9orf72 expansions and the important neuropathological overlap of cytoplasmic inclusions of TAR DNA binding protein 43 (TDP-43) in both disorders." (PMID 23498975, 2013). "Formation of TAR-DNA binding protein (TARDBP, also known as TDP43)-positive intracellular inclusions in the central nervous system (CNS) is the most common pathology in the patients with ALS and frontotemporal lobar degeneration (FTD), even in the absence of TDP-43 mutations." (PMID 23281774, 2013).